MMP2 (matrix metallopeptidase 2)
Diseases named in the same sentence as MMP2 in open-access papers (continued):
Sharing a sentence is not in itself a finding about the gene and the disease.
ovarian carcinoma (continued). "Matrix metalloproteinases (MMPs) secreted by cervical and ovarian cancer, especially MMP-2 and MMP-9, play crucial roles in tumor invasion and metastasis." (PMID 25686833, 2015). "Cisplatin-induced EMT is correlated with reduced E-cadherin and increased vimentin, Snail, Twist, and matrix metalloproteinase (MMP)-2 expression in ovarian cancer cells." (PMID 25839165, 2015). "The results of these measurements showed that highly metastatic cancer cells had a 5–6 - fold higher expression of MMP2 mRNA when compared with A2780 ovarian cancer cells." (PMID 24919932, 2014). "In conclusion, we have provided evidence that catalpol suppresses proliferation and facilitates apoptosis of OVCAR-3 ovarian cancer cells through upregulation of microRNA-200 and downregulation of MMP-2 expression." (PMID 25347277, 2014). "It is concluded that catalpol suppressed cellular proliferation and accelerated apoptosis in OVCAR-3 ovarian cancer cells via promoting microRNA-200 expression levels and restraining MMP-2 signaling." (PMID 25347277, 2014). "We found that SDHB silencing promoted ovarian cancer invasion and migration accompanied with up-regulated expression of MMP-2 and p-FAK." (PMID 25491408, 2014). "A previous study indicated the modulatory effects of claudins on MMP-2 activation in ovarian cancer cells." (PMID 25120725, 2014). "ANXA2 was shown to promote the invasion and metastasis of ovarian cancer cells through the activation of MMP2." (PMID 25362534, 2014). "In the intraperitoneal model of ovarian cancer, the administration of MMP2/LHRH Mn3O4 NPs not only increase signals in the cancer masses, but also allowed for outline of their shapes." (PMID 24919932, 2014). "Administration of MMP2/LHRH Mn3O4 NPs into a subcutaneous ovarian cancer model resulted in a significant increase in MR signal intensity." (PMID 24919932, 2014). "E2 has been found to increase the metastatic potential of human epithelial ovarian cancer cell through upregulation of MMP-2 and downregulation of E-cadherin." (PMID 24222765, 2013). "It is reported that the rate of MMP2 expression in ovarian cancer is high and irrelevant with either clinical staging or histological typing." (PMID 23384043, 2013). "Based on these results, RPS7 appears to influence ovarian cancer cell invasion and migration possibly through regulation of MMP2, E-cadherin, and β-catenin." (PMID 24244431, 2013). "To study the effect of minocycline on MMP activity in ovarian cancer cells, we analyzed the expression of MMP-2 and MMP-9 in SKOV-3 cells after treatment with varying concentrations of minocycline for 18 h." (PMID 23593315, 2013). "Id1 and MMP-2 expression were increased in EPCs freshly isolated from ovarian cancer patients compared to those obtained from healthy subjects." (PMID 23714001, 2013). "MMP-2 and MMP-9, in particular, have been found to be specifically associated with ovarian cancer metastasis." (PMID 23566400, 2013). "Expression of claudin-6, occludin, and MMP2 was detected in samples of human ovarian cancer tissues by immunohistochemistry and correlated with the clinical properties of the tumors." (PMID 24245968, 2013). "There were no apparent correlations between expression of claudin-6, occludin and MMP-2 in ovarian cancer tissue (P > 0.05)." (PMID 24245968, 2013). "Claudin-6 and MMP-2 can be used as important indicators for the judgment of malignant behavior of ovarian cancer such as invasion and metastasis." (PMID 24245968, 2013). "This is in line with Kenny and al data where they described mesenchymal cells-derived fibroblasts promote ovarian cancer cell migration and invasion in a MMP2 dependant manner." (PMID 22666502, 2012). "Studies indicate that MMP-2 is predominately important in early tumorgenesis by initiating metastasis through enhancing adhesion of ovarian cancer cells to the peritoneum." (PMID 22022379, 2011).
ovarian carcinoma (continued). "In particular, MMP-2 and MMP-9 are consistently upregulated in ovarian cancer and are associated with poor prognosis." (PMID 22022379, 2011). "Based on our data, there are many more MMPs beside the commonly investigated MMP-2, -9 and -14, which are expressed in ovarian cancer cell lines and are thus candidates for future analyses on their influence on the development of ovarian cancer." (PMID 20942921, 2010). "In ovarian cancer, MMP-2 and -9 seem to be expressed more frequently in early lesions than in established carcinomas." (PMID 20942921, 2010). "Overexpression of MMP-2, -9 and -14 seems to also prepare the ground for development and growth of malignant ovarian tumors." (PMID 20942921, 2010). "Ovarian cancer cells express MMP2 and MMP9, and we and others have shown that increased expression of MMPs is associated with cancer cell invasiveness and metastatic potential." (PMID 17567918, 2007). "Upregulation of MMP-2 is seen in solid tumours including hepatocellular, colorectal and ovarian cancers." (PMID 12771921, 2003). "This study investigated the impact of siRNA-mediated MEG3 silencing in the context of dendrosomal nanocurcumin (DNC) and Oxaliplatin (OXA) treatments on ovarian cancer cell lines, focusing on the expression of genes associated with apoptosis and metastasis, including Bcl-2, BAX, MMP-2, and MMP-9." (PMID 41480643, 2026). "The results indicated that Kirenol has the potential to inhibit metastasis, as shown by its ability to reduce the migratory capacity of ovarian cancer cells and decrease the expression of key factors involved in cell migration and invasion, including MMP-2 and MMP-9." (PMID 38415456, 2025). "In addition, OA-Ir and OA-Ru effectively suppressed the metastasis of ovarian cancer cells through the mechanism of suppressing MMP2/MMP9 and disrupting F-actin dynamics." (PMID 40362572, 2025). "Since matrix metalloproteinase 9 (MMP9) and MMP2 are upregulated in ovarian cancer and their activity is correlated with invasion and metastasis, we hypothesized that the impact of LKB1 and STRADα on EOC invasion is mediated by MMP activity." (PMID 39594681, 2024). "Triptolide, a diterpenoid epoxide from the thunder god vine, Tripterygium wilfordii, has proapoptotic activity and anti-tumor effects in ovarian cancer cells, reducing the expression of sorcin, MMP-2, and VEGF, which are usually highly expressed in ovarian cancer cells." (PMID 39199583, 2024). "The purpose of the present study was to determine the diagnostic utility of selected MMPs, MMP-2, MMP-3, MMP-11 and MMP-26, as new biomarkers in patients with ovarian cancer and to compare the results obtained with routinely determined markers CA125 and HE4 and the ROMA algorithm." (PMID 38892452, 2024). "Thus, in SKOV-3 cells, GnRH2 inhibits ovarian cancer invasion by regulating the balance of MMP2/TIMP2, and disrupting AKT-mediated proteolysis and invasion." (PMID 38260130, 2023). "In ovarian cancer, the expression of Slug is positively correlated with that of MMP2." (PMID 37143106, 2023). "Endogenous MMP2 also plays a role in promoting ovarian cancer cell invasion." (PMID 38203692, 2023). "In addition, baicalein cooperating with cisplatin suppresses MMP2 protein expression and cell metastasis of resistant ovarian cancer cells, through regulation of CirSLC7A6/miR-2682-5p/SLC7A6." (PMID 37940982, 2023). "OXT inhibited ovarian cancer metastasis by suppressing the expression of MMP-2 and VEGF." (PMID 36172369, 2022). "Moreover, 3,4′,7-O-trimethylquercetin, a quercetin derivative, inhibits the invasion of ovarian cancer cells by suppressing the expression of uPA and MMP2." (PMID 35621926, 2022). "Furthermore, the inhibition of MMP2 activity reduced the attachment of ovarian cancer cells in a 3D organotypic model of metastatic ovarian cancer." (PMID 35954423, 2022). "Increased expression of MMP2 was confirmed in both benign and malignant ovarian cancer cells." (PMID 36012171, 2022).
ovarian carcinoma (continued). "PCGEM1 overexpression might cause carcinogenesis in ovarian cancer and affect its development by modulating YAP, P70S6K, RhoA, Bcl-xL and MMP2 protein levels." (PMID 35109849, 2022). "PGI2 has been described to act as an anti-metastatic mediator in lung cancer mouse models and to suppress ovarian cancer cell invasion by MMP2/MMP9 downregulation in vitro, whereas other studies reported an association of PTGIS expression with reduced survival of breast and ovarian cancer patients." (PMID 36551640, 2022). "Among them, MMP9 regulates cell–cell adhesion by catalyzing E-cadherin ectodomain shedding to mediate metastatic dissemination, whereas MMP2 mediates the peritoneal adhesion of ovarian cancer cells by cleaving the extracellular matrix proteins fibronectin and vitronectin into small fragments." (PMID 35860572, 2022). "Thus, to inhibit ovarian cancer cell invasion, it is important to regulate the activation and expression levels of MMP2 and MMP9." (PMID 35621926, 2022). "Furthermore, exosomal circPUM1 derived from CAOV3 ovarian cancer cells promoted tumor metastasis of peritoneal mesothelial cells via upregulation of nuclear factor (NF)-κB and matrix metallopeptidase 2 (MMP2) expression." (PMID 35024437, 2022). "Additionally, a meta-analysis found that high levels of MMP-2 correlated with lower overall survival in ovarian cancer patients." (PMID 36077825, 2022). "To determine if this observed limited invasive capacity resulted from decreased extracellular matrix remodeling activity, as a proof-of-concept we next determined MMP2 and LOX protein expression in drug-treated spheroids since these proteins are associated with ovarian cancers’ invasive capacity." (PMID 36727073, 2022). "Norepinephrine can increase the expression of VEGF in ovarian cancer cells and promote the migration of endothelial cells by inducing the expression of MMP-2 and MMP-9, thereby inducing the formation of new blood vessels in tumors." (PMID 34307378, 2021). "The cytotoxic effect of the melittin-containing conjugate on cancer cells with higher activity of MMP2 was proven in this study, for example, in the investigated prostate cancer cell line and the additionally investigated ovarian cancer cell line (SK-OV-3 cells)." (PMID 34067049, 2021). "It has been previously shown that MMP2 functions as an early marker for ovarian cancer metastasis." (PMID 34040530, 2021). "Considering the well-characterized role of MMP-9 and MMP-2 in the metastases of many cancers, including ovarian cancer, we investigated whether CCL7-induced ERK activation mediated the expression of these enzymes." (PMID 34206004, 2021). "Auraptene has been reported to decrease the viability of human cervical and ovarian cancer cells and suppresses the migration and invasion of Hela and A2780 cell line by reduction of matrix metalloproteinase-2 (MMP-2) and metalloproteinase-9 (MMP-9) enzymatic activity, respectively." (PMID 34239445, 2021). "Interestingly, IL-8 was shown to increase cell proliferation and correlate with increased MMP2 expression in ovarian cancer." (PMID 34040530, 2021). "Moreover, ADSCs stimulate ovarian cancer cell proliferation and metastasis by producing MMP2 and MMP-9 proteins." (PMID 34440886, 2021). "Additionally, the authors, in their investigations on cervical and ovarian cancer cells, observed a Pug-induced reduction in matrix metalloproteinases (MMP2 and 9) paralleled by a rise in their inhibitors (TIMP2 and 3)." (PMID 34444893, 2021). "As exhibited in the previous studies, decreased MMP-2 and MMP-9 expression has been shown to be associated with inhibited metastatic capacity in multiple human tumors, such as gastric cancer, colon cancer, ovarian cancer and HNSCC." (PMID 34587874, 2021). "Iloprost could reduce the expression of matrix metallopeptidase-2 and then attenuate ovarian cancer progression." (PMID 34440557, 2021).
ovarian carcinoma (continued). "Thus, LPS and IL-8 stimulated UCB-derived neutrophils to inhibit invasion and migration by down-regulating N-cadherin, MMP-2 and up-regulating E-cadherin expression in ovarian cancer cells." (PMID 32489460, 2020). "Results from the present study also demonstrated that KLF7 silencing reduces expression and activity of MMP2, a gelatinase shown to be secreted and activated in ovarian cancer and closely correlated with invasion and metastasis of cancer cells and poor survival." (PMID 33250051, 2020). "Furthermore, our study dissects that UCB-derived neutrophils suppressed ovarian cancer cells metastasis through regulation E-cadherin, N-cadherin, and MMP-2 which were mesenchymal-epithelial transition-related signaling." (PMID 32489460, 2020). "Previous studies have described the expression of MMPs in epithelial ovarian cancer and evaluated the presence of MMP-2 and MMP-9 in the tumor as potential biomarkers of aggressiveness of the malignancy, registering the disease-free period and the overall survival of patients." (PMID 32718331, 2020). "Our results indicated that the knockout of the EGFL6 gene could inhibit EMT in ovarian cancer cells by upregulating the expression of E-cadherin and downregulating the expression of N-cadherin, MMP2, MMP9, and Vimentin." (PMID 32983976, 2020). "Furthermore, in an in vivo ovarian cancer xenograft model, omental adipose-derived MSCs were found to promote the formation of peritoneal metastasis via the upregulation of MMP-2 and MMP-9 expressions." (PMID 30568223, 2019). "In ovarian cancer cells, NC treatment led to the inhibition of migration and invasion through regulation of MMP-2/9 (Matrix metalloproteinase 2/9) and Skp2 (S-phase kinase-associated protein 2).27, 28 Altogether, without a doubt, NC exerts its anti-tumor activity in various types of human cancers." (PMID 30847386, 2019). "Overexpression of the lncRNA PCGEM1 (prostate cancer gene expression marker 1) promotes cancer growth by upregulating protein expression of RhoA and its downstream factors YAP (Yes-associated protein), MMP2 (matrix metalloproteinase 2), Bcl-xL and P70S6K in ovarian cancer." (PMID 31248165, 2019). "Additionally, other studies demonstrated that MMP-2 and MMP-14 are also overexpressed in ovarian cancer samples, which is associated with poor clinical outcome." (PMID 31612116, 2019). "In addition, it inhibits the cancer-promoting factors, including VEGF, MMP9, MMP2, and IL-10, in macrophages stimulated by ovarian cancer cells." (PMID 30871059, 2019). "Interestingly, it was observed that VEGFR-2, plexin-B1, and Sema4D control the expression of CD31, MMP-2, and VE-cadherin in ovarian cancer cells, which are the markers and initiators of angiogenesis and VM." (PMID 31612116, 2019). "A previous study has also shown that MMP-14 could activate MMP2, both of which appeared to play important roles in regulating cell growth and proliferation by controlling matrix remodeling in aggressive ovarian cancer cells." (PMID 31406154, 2019). "Other studies showed that phospho-STAT3 triggered abnormal dimerization of STAT3, increased the expression of anti-apoptotic proteins Bcl2, Bcl-xl, and MMP2/9, and promoted proliferation, survival, and migration/invasion in ovarian cancer, liver cancer and retinoblastoma cells." (PMID 31422383, 2019). "Taken together, our results show that circPUM1 upregulates NF-κB and MMP2 by sponging miR-615-5p and miR-6753-5p and releasing their inhibitory effect on the expression of these two targets, thus promotes tumorigenesis and progression of ovarian cancer." (PMID 31751911, 2019). "Over expression of MMP-2 in the peritoneal implants, but not in the primary tumors, of ovarian cancer patients have been related to a significant risk of death." (PMID 29393911, 2018). "We evaluated secretion of markers of angiogenesis, VEGF and MMP2, by ovarian cancer cells." (PMID 30131543, 2018).
ovarian carcinoma (continued). "A meta-analysis of 956 ovarian cancer patients from 8 independent studies demonstrated that tumor-derived MMP-2 expression can predict a lower overall survival rate and could be used as an independent negative prognostic factor." (PMID 29393911, 2018). "However, another study on ovarian cancer showed that β4-integrin depletion reduced the expression of MMP-2 and MMP-9, consistent with our data." (PMID 29190919, 2017). "Western blot showed that miR-519d transfection in ovarian carcinoma cells downregulated RhoC (Ras homolog gene family member C), Bcl-2, cyclin D1, survivin, MMP2, MMP9, STAT3 (signal transducer and activator of transcription 3), and HuR (ELAV-like RNA-binding protein 1) expression (P < 0.05)." (PMID 28146423, 2017). "Tumor-derived MMP-2 expression predicts a lower overall survival rate and could be an independent prognostic factor in patients with ovarian cancer." (PMID 28538838, 2017). "HIF‐1α binds to AEG‐1 promoter and induces upregulated AEG‐1 expression to enhance metastasis in ovarian cancer by increasing MMP2 and MMP9 expression as well as attenuating E‐cadherin and β‐catenin expression during hypoxia, which is a typical feature of tumor microenvironment." (PMID 28401704, 2017). "MMP-2 plays a positive role in the invasion and metastasis of ovarian cancer." (PMID 28538838, 2017). "As a result, a detailed molecular characterization of regulation of MMP-2 could further highlight STAT3 as an effective drug target for ovarian cancer." (PMID 28859117, 2017). "Tumor-derived MMP-2 expression predicts a lower overall survival rate and therefore might be an independent prognostic factor for ovarian cancer." (PMID 28538838, 2017). "Therefore, our illustration demonstrated that cRGD inhibited VM formation in ovarian cancer via not only down-regulating uPA expression which reduced MMP-2 efficiency to cleave Laminin5γ2 through AKT/mTOR/MMP-2/Laminin5γ2 signal pathway but also reducing EMT." (PMID 26992227, 2016). "Earlier reports indicated a prognostic value for both MMP-14 and MMP-2 in ovarian cancer." (PMID 27038607, 2016). "Therefore, MMP-2 and Laminin5γ2 enabled to act as evaluation proteins to assess VM formation in ovarian cancer." (PMID 26992227, 2016). "The mechanisms responsible are related to MMP-2-mediated cleavage of vitronectin and fibronectin to generate fragments that interact with integrin receptors α5β1 and αvβ3, which promote the adhesion of ovarian cancer cells lining the peritoneal cavity." (PMID 27634880, 2016). "It has been shown that miR-138 may have an effect on tumor metastasis by targeting SOX4 and HIF1a in ovarian cancer and targeting MMP2/MMP9 in cholangiocarcinoma." (PMID 25845814, 2015). "Notably, we found that the activity of MMP-2 was much higher than the MMP-9 activity in ovarian cancer cells." (PMID 25686833, 2015). "In order to verify this hypothesis, we measured the MMP2 expression in established ovarian cancer cells and highly metastatic cancer cells isolated from malignant ascites obtained from patients with advanced ovarian carcinoma using quantitative PCR." (PMID 24919932, 2014). "Here, also consistent with our previous data, we report that OPNc-overexpressing cells induce Mmp2 and Mmp9 overexpression in ovarian carcinoma and prostate cancer cells, respectively, further corroborating a role of these gene products in activating cell invasion in both tumor models." (PMID 24928374, 2014). "Matrix metalloproteinase-2 (MMP-2) is closely related to the pathogenesis of ovarian cancer." (PMID 25347277, 2014). "In summary, these data support the rationale of pharmacologic inhibition of the Id1/NF-κB/MMP-2 or Id1/PI3K/Akt pathways for ovarian cancer therapy and suggest that inhibition of Id1 or its downstream molecule MMP-2 removes the protection of ovarian cancer EPC from angiogenesis." (PMID 23714001, 2013).